KLF4 (KLF transcription factor 4)
Diseases named in the same sentence as KLF4 in open-access papers (continued):
Sharing a sentence is not in itself a finding about the gene and the disease.
cancer (continued). "Further investigation of ALDH1A1, MAOA, and particularly KLF4 in a patient cohort is warranted, and their involvement in maintaining cancer stem cell populations could lead to novel areas of investigation for non-surgical treatment of EEC and LNG resistance." (PMID 38635728, 2024). "In fact, existing studies show that KLF4 has different effects in different tissues or cancers." (PMID 38546623, 2024). "Interestingly, NOTCH-1 performs an inhibitory effect on KLF4 to regulate the proliferation and differentiation of cancer cells." (PMID 36761967, 2023). "In our present study, we found that miR-7-5p could inhibit radioresistance through suppressing the cancer cell stemness by directly targeting KLF4 in CRC cells." (PMID 36732504, 2023). "However, KLF4 inhibits cancer cell proliferation, EMT, invasion and metastasis in the advanced stage." (PMID 37031197, 2023). "NANOG and KLF4 are transcriptional factors regulating cancer stem cell phenotype." (PMID 37283789, 2023). "Cancer cells sustain growth under metabolic stress due to the Warburg effect, so KLF4 downregulation is involved in metabolic pathways that respond to low glucose, increased reactive oxygen species (ROS), and decreased autophagic response to glucose starvation." (PMID 36661515, 2023). "The inhibitory effect of KLF4 on cancer cells proliferation may be related to the suppression of survivin." (PMID 37031197, 2023). "Further studies suggest that KLF4’s inhibition of cancer may be mediated by downregulating the TGF-β1-mediated extracellular regulated protein kinases (ERK)/JNK/NF-κB signaling pathway." (PMID 36761967, 2023). "The increased methylation level of CpG sites in the KLF4 promoter and decreased expression level of KLF4 in BC tissues lead to the resistance to paclitaxel, which has become the target of 3,3’-diindolylmethane in improving the effectiveness of cancer chemotherapy." (PMID 36761967, 2023). "KLF4 maintains stem cell self-renewal in homeostasis and cancer." (PMID 36761967, 2023). "Restoring of KLF4 in miR-7-5p-overexpressing HCT116-R cells could rescue the decreased cancer stemness and the attenuated radioresistance regulated by miR-7-5p." (PMID 36732504, 2023). "However, in a nutrient-deprived environment, KLF4 protects cells from death by blocking the cell cycle and inhibiting apoptosis, and cancer hijacks the mitochondrial machinery to drive cell survival." (PMID 36761967, 2023). "In addition, KLF4 is an important stem-cell-inducing factor that help cancer stem cells to acquire and maintain their CSC properties." (PMID 36732504, 2023). "Mechanically, the RAS/RAF/MEK/ERK signaling pathway upregulates the expression of E2F transcription factor 1 (E2F1), which binds to the promoter of KLF4, thereby increasing the expression of KLF4 at the protein and mRNA levels and reducing the apoptosis of cancer tissues." (PMID 36761967, 2023). "However, in HPV-mediated cancers, there is evidence that KLF4 modulation is mediated by the two HPV proteins E6 and E7." (PMID 37876935, 2023). "Our investigations revealed that Dicer silencing was correlated with an increase in the mRNA and protein expression levels of the following cancer stem cell–related transcription factors, as indicated by qRT-PCR and Western blotting: Oct-4, Nanog, KLF4, and SOX2." (PMID 37976135, 2023). "The KLF4 transcription factor plays a context-dependent role in carcinogenesis and may be up or downregulated in distinct types of cancer." (PMID 37559082, 2023). "Thus, we accessed The Cancer Genome Atlas Program (TCGA) and Catalogue of Somatic Mutations in Cancer (COSMIC) databases and acquired a list of mutations in KLF4 and KLF5 in samples obtained from CRC patients." (PMID 37173904, 2023).
cancer (continued). "KLF4 typically promotes apoptosis in cancer cells but also exerts anti-apoptotic effects." (PMID 36761967, 2023). "It is widely believed that HCC patients with elevated KLF4 levels are more susceptible to immune checkpoint blockades (ICBs) and that targeting KLF4 could affect exhausted T cell reprogramming to improve immune responses to cancer cells." (PMID 36936440, 2023). "Based on cancer stem cell hypotheses, not only coding transcripts such as Oct4, Nucleostemin, Sox2, and Klf4, but also long non-coding transcripts, contribute to regulating CSC proliferation." (PMID 37104007, 2023). "Meanwhile, KLF4 level was decreased in cancer cell lines, and overexpressing miR-135b-5p could inhibit the expression of KLF4." (PMID 35027543, 2022). "A previous study found that enforced KLF4 expression could decrease LDHA expression in cancer cells, thereby forming a KLF4/LDHA signaling pathway to regulate aerobic glycolysis." (PMID 35757505, 2022). "Furthermore, by targeting pluripotency factors like OCT4, SOX2, and KLF4 in various cancers, miR-145-5p has been shown to suppress the cancer stem cell-like properties and contribute to chemotherapy and radiation sensitivity." (PMID 35368699, 2022). "Similarly, KLF4 can negatively regulate the expression of EMT that is closely associated with the proliferation, invasion, and metastasis of cancer cells including breast cancer and colorectal cancer." (PMID 35637651, 2022). "Considering the involvement of KLF4 in chemoresistance in cancer, we sought to investigate whether DUB3 regulates the response of HCC cells to chemotherapy through KLF4." (PMID 35383144, 2022). "KLF4 plays important roles in development, cellular reprogramming and cancer." (PMID 35177016, 2022). "Moreover, ZEB1 has been associated with the development of the cancer stem cell (CSC) phenotype through the regulation of miRNAs controlling the expression of stemness transcription factors such as SOX2 and KLF4." (PMID 35682554, 2022). "On the other hand, the aberrant expression of L1 has been linked to the development of human carcinomas, influencing DNA damage responses and bestowing cancer stem cell-like properties, including KLF4 (Krüppel-like factor-4) and CD44 (well-established markers of stemness)." (PMID 36142795, 2022). "KLF4 is differentially expressed in different types of cancer." (PMID 35383144, 2022). "KLF4 is also considered a tumour suppressor gene in various cancers." (PMID 36518312, 2022). "Interestingly, SIRT1 gene silencing upregulated the expression of the EMT-related protein E-cadherin and cancer stemness markers kruppel-like factor 4 (KLF4) and aldehyde dehydrogenase 1 family member A1 (ALDH1A1)." (PMID 36291902, 2022). "Interestingly, besides its known role in pluripotency determination, KLF4 has been reported to inhibit cancer cell proliferation both in NSCLC and in CRC." (PMID 36077264, 2022). "Indeed, ALDH1A1 controls cell cycle checkpoints by regulating KLF4 and p21 proteins, which contribute to apoptosis inhibition in cancer stem cells." (PMID 36551502, 2022). "In addition, cell experiments also suggested that overexpressing KLF4 hindered malignant behaviors of cancer cells, but the inhibitory effect was reduced by miR-135b-5p." (PMID 35027543, 2022). "Therefore, Helicobacter pylori can play a role in promoting cancer by inhibiting the KLF4 expression." (PMID 34367275, 2021). "The overexpression of KLF4 is in favor of enhancing CP-mediated apoptosis in cancer cells." (PMID 33921908, 2021). "Some research has been performed on KLF4′s regulation of metabolism, but little is known about this process and how it may relate to cancer." (PMID 33917010, 2021). "KLF4 can also promote stemness in various cancers where it promotes epithelial differentiation, thereby challenging the tacitly assumed association between EMT and cancer stem cells (CSCs)." (PMID 34680284, 2021).
cancer (continued). "Some pluripotent markers, such as Klf4, Nanog, and Myc, have important roles in maintenance of the undifferentiated state of cancer cells, negatively correlated with treatment outcomes in cancer patients." (PMID 33890571, 2021). "Of course, more research is needed to verify this hypothesis and to elucidate how cancer cells induce KLF4 upregulation in response to exogenous stimulation or endogenous oxidative stress." (PMID 34040532, 2021). "Furthermore, LR004-VC-MMAE treatment also significantly reduced the expression of various cancer stemness marker genes, including Oct4, Sox2, KLF4 and EpCAM." (PMID 34879870, 2021). "Cancer cells that dysregulate KLF4 may exhibit a more Warburg-like response to stressors, in addition to resisting cell death and undergoing increased mutability due to ROS buildup." (PMID 33917010, 2021). "KLF4 plays an important role in physiology and several pathological processes like inflammation and radiation injury that outreach the subject of this review, but most notably in the development and progression of cancer." (PMID 35008527, 2021). "Several factors known to play a central role in embryonic stem cells and used in epigenetic reprogramming, such as pluripotency factors OCT4, NANOG, SOX2 and Klf4, have been reported to be expressed in subpopulations of cancer cells from different tumour types." (PMID 33453053, 2021). "Finally, the epigenetic influence mediated by KLF4 on EMT can change the phenotypic distribution in a heterogeneous cancer cell population." (PMID 34680284, 2021). "Importantly, it has been reported that KLF-4, another cancer stem factor, binds the HPV31 promoter and increases viral transcription through two regions of the HPV31 LCR, activating both early and late promoters." (PMID 34452350, 2021). "As their levels decrease simultaneously, KLF4 upregulation may promote ROS levels in enhancing CP sensitivity of cancer cells." (PMID 33921908, 2021). "Osteosarcoma cells that overexpressed KLF4 displayed characteristics of cancer stem cells." (PMID 35008527, 2021). "Moreover, Krüppel-like factor 4 (KLF4) was identified as a direct target of miR-92a-3p, and an obvious inverse correlation was observed between the expression of miR-92a-3p and KLF4 in 40 pairs of cancer tissues." (PMID 35095494, 2021). "As it has been reported that apoptosis-inducing function of NOXA is suppressed in constitutive NOXA-high expressing cancer cells—especially in hematopoietic cancers —we considered that increasing the induction of NOXA by KLF4 in L-lines enhances the induction of apoptosis." (PMID 33918002, 2021). "Furthermore, inducible expression of SOX2, OCT4 and KLF4 in melanoma cells leads to partial reprogramming of these cancer cells which start exhibiting increased invasion potential and lung colonization." (PMID 33453053, 2021). "KLF4 was found to increase and act as an oncogene in several cancers, including OS." (PMID 33828977, 2021). "PI3K/AKT was shown to be a downstream signaling pathway of KLF4 in the study of carcinoma." (PMID 34925023, 2021). "Given the critical role of KLF4 in maintaining cellular integrity, one would expect that de-regulation of KLF4 function, therefore, would lead to substantial disruption in cellular architecture, integrity and maintenance, and may even directly lead to cancer." (PMID 33266506, 2020). "KLF4 is very important for maintaining the stemness in cancer cells." (PMID 33266506, 2020). "Although the mechanism(s) underlying these discrepancies remain unclear, evidence suggests that KLF4 plays an important role in cancer and highlights the need for further characterization of the specific role of KLF4 in CSCs." (PMID 33052880, 2020). "In addition, further in vitro experiments showed that miR-7 reduces the ability of invasion and self-renewal of cancer stem cells (CSCs) by modulating KLF4 expression." (PMID 33266506, 2020).
cancer (continued). "Interestingly, recent studies indicate a new role for KLF4 in various cancers involving regulating the self-renewal and maintenance of cancer stem cell populations." (PMID 32408542, 2020). "It appears that KLF4 participates in the response of cancer cells to chemotherapy." (PMID 33266506, 2020). "Moreover, a controversial role of KLF4 in regulating EMT in gastrointestinal cancer has been described, as currently, the mechanisms underlying its controversial role in this cancer type remain undefined." (PMID 32156068, 2020). "The inconsistency in and discrepancy among KLF4 reports may also reflect the pleiotropic functions of this protein and complexity in cancers, especially in hepatocarcinogenesis." (PMID 32408542, 2020). "We speculate that this may be due to the fact that CF cells display a partial EMT/cancer-like phenotype, which leads to altered signaling pathways, namely those linking KLF4 to CFTR." (PMID 32630830, 2020). "Actually, the roles of SETD7 and KLF4 in cancers are controversial." (PMID 32126149, 2020). "It has been reported that the use of radiation to destroy cancer cells after surgery may convert differentiated cancer cells to CSCs through the expression of CSC markers such as Oct4/Sox2/KLF4." (PMID 32426267, 2020). "Immunohistochemical experiments found that KLF4 expression was significantly increased in the adjacent normal tissues compared to that in the carcinoma tissue and was significantly decreased in GC patients with positive H pylori infection compared with expression in those without H pylori infection." (PMID 32017451, 2020). "The expression and activity of KLF4 in human cancers are different." (PMID 31724937, 2019). "Furthermore, the ability of α‐Mangostin to suppress the expression of pluripotency maintaining genes Oct4, Sox2, KLF4 and c‐Myc suggest that it can directly control cancer stem cells, proliferation, pluripotency and self‐renewal." (PMID 30712329, 2019). "In addition, the expression of a zinc finger protein, KLF4 (Kruppel-like factor 4) was found to be regulated by miR-10b in certain cancer cell lines." (PMID 31293964, 2019). "Indeed, molecules including TGF-β, Notch, Runx, and KLF4, exhibit opposite functions in different cancer settings." (PMID 31092229, 2019). "Taken together, these observations indicate a context-dependent role of KLF4 in cancer." (PMID 31245293, 2019). "Furthermore, during ethanol‐induced cellular transformation, cells gained the phenotypes of cancer stem cells (CSCs) by expressing pluripotency maintaining factors (Oct4, Sox2, cMyc and KLF4) and stem cell markers (CD24, CD44 and CD133)." (PMID 29761897, 2018). "PARP1 recruits KLF4 to activate telomerase expression in cancer cells." (PMID 29899271, 2018). "Interestingly, among the genes that are regulated by TRPM7, SOX2, CD133 and KLF4 are cancer stemness markers." (PMID 30477473, 2018). "Amounts of previous studies focused on KLF4’s role in cancer development and progression." (PMID 30297986, 2018). "Specifically, KLF4 has been shown to negatively regulate EMT in cancers." (PMID 29375271, 2018). "Downregulation of LINCROR by miR-145 might impair the cancer stemness by deregulation of another transcription factor KLF4." (PMID 29719612, 2018). "Indeed, KLF4 is activated in diverse human cancers and predictive of mortality; however, the molecular mechanisms by which KLF4 is driven to induce CSCs remain less well documented." (PMID 30038266, 2018). "Downregulation of KLF4 in several cancers, such as colon, gastric, esophageal, prostate and lung may contribute to cellular hyperproliferation and malignant transformation, which is consistent with its role in cell cycle arrest and apoptosis." (PMID 29899271, 2018). "Overexpression of KLF4 obviously affected cancer cell proliferation, invasion and metastasis." (PMID 28938633, 2017). "Data from multiple cancers indicated that Klf4 can have divergent functions in EMT." (PMID 29212199, 2017).
cancer (continued). "Briefly, a total of 17 studies including 2188 patients with distinct kinds of cancers yielded statistics, combined HRs, indicating significantly negative effect of loss of KLF4 expression on patients' survival time." (PMID 29062163, 2017). "Klf4 were then proposed to play a essential role in cancer stem cells (CSCs)." (PMID 29212199, 2017). "For example, oncogenic miRNAs such as miR-103 and miR-92a could promote cancer cell proliferation, invasion, and migration by inhibiting the expression of KLF4." (PMID 29062163, 2017). "Down-regulation of both c-Myc and Klf4 in reprogrammed OSCC suggests reprogramming may initiate an epigenetic reversal process on the oncogenic gene networks in cancer cells and this phenomenon could be utilized as a therapeutic strategy for treatment of OSCC." (PMID 28417059, 2017). "KLF4 also functions as a cancer driver gene, and is involved in cancer stem cell maintenance." (PMID 28553926, 2017). "KLF4 is a potential oncogene in patients with various cancers." (PMID 28380435, 2017). "Klf4 plays a divergent role in various cancers, depending on different cell context." (PMID 29212199, 2017). "In addition, Wnt/β-catenin signaling keeps the stemness of cancer stem cells via up-regulating stem cell-related transcription factors Oct4, Sox2, c-Myc, Nanog and KLF4." (PMID 28350360, 2017). "Given that KLF4 has been shown to suppress hTERT expression and cell growth, we examined whether hTERT could contribute to KLF4-mediated inhibition of cancer cell proliferation." (PMID 27153563, 2016). "Thus, we decided to screen an additional panel of 21 human cancer cell lines from various origins for the expression of KLF4 all, KLF4(FL), and KLF4α." (PMID 27323810, 2016). "KLF4 has also been shown to be a critical regulator of lytic Epstein Barr virus (EBV) replication underscoring the importance of this cellular transcription factor in the life cycles of multiple human cancer viruses." (PMID 27386862, 2016). "Furthermore, the qRT‐PCR results also showed a significantly decreased mRNA expression of Nanog, Klf4, survivin, and β‐catenin in napabucasin treatment with PC‐3 stemness‐high cancer cells (P < 0.05)." (PMID 26899963, 2016). "Additionally, KLF4 plays a prominent role in the maintenance of the cancer stem cell-like population, which promotes cell migration and invasion." (PMID 27323810, 2016). "Although more evidence of how KLF4 induce senescence in vivo is needed, our results strongly implied that KLF4 might resist cancer progression through promoting cellular senescence." (PMID 27531889, 2016). "The result implied that KLF4 overexpression might induce senescence and predicted better prognosis in cancer patients." (PMID 27531889, 2016). "On the contrary, deletion of KLF4 in mice model promotes carcinogenesis in many types of cancers." (PMID 27531889, 2016). "Recent studies have described an ambivalent role for KLF4 in cancer progression." (PMID 27105535, 2016). "However, we noted that both EGFR and KLF4 mRNAs are known targets of microRNA-7 (miR-7) in human cancer cells." (PMID 26840086, 2016). "In addition, cancer cells transfected with Ad-KLF4 had profoundly decreased hTERT activity, especially in H1299 cells." (PMID 27153563, 2016). "In addition, in some other cancers such as breast and oral squamous cell carcinoma, KLF4 was found to be increase and act as an oncogene." (PMID 27105535, 2016). "Stem-cell-specific transcription factors (e.g., Sox2, Klf4, Oct4, and Nanog) are frequently encountered in human cancers, and their transcriptional networks are necessary for the development and maintenance of cancer stem-like cells." (PMID 26322272, 2015). "In the course of our study, KLF4 proved to be the direct target of miR-29 in cancer cell lines." (PMID 26020233, 2015).